CCL2 (C-C motif chemokine ligand 2)
Diseases named in the same sentence as CCL2 in open-access papers (continued):
Sharing a sentence is not in itself a finding about the gene and the disease.
prostate carcinoma (continued). "In this model system, cross-communication significantly increased CCL2 expression by both prostate cancer and U-937 cells and lead to increased prostate cancer cell invasion and NF-κB activation." (PMID 26317041, 2015). "Administration of monoclonal antibodies against CCL2 reduced recruitment of inflammatory monocytes and inhibited metastasis to lung in breast cancer, prostate cancer and it is currently being evaluated in ovarian cancer." (PMID 26062132, 2015). "The CCL2 expression increased in both the prostate cancer cells and monocytes with the greatest increase in the cancer cells." (PMID 26317041, 2015). "Prostate cancer cell NF-κB DNA binding activity depended on CCL2 dose and was inhibited by CCL2 neutralizing antibodies." (PMID 26317041, 2015). "Prostate cancer tissues were immunostained to analyze prostate cancer macrophage, CCL2 and NF-κB subunit localization." (PMID 26317041, 2015). "The experiments also demonstrated that CCL2 was the key factor increased in the co-cultures that stimulated prostate cancer cell invasion and NF-κB activity." (PMID 26317041, 2015). "Newly demonstrated, prostate cancer cells were stimulated to increased invasion by CCL2 and monocyte co-cultures in a NF-κB-dependent manner." (PMID 26317041, 2015). "The current study demonstrates that prostate cancer/monocyte co-cultures expressed high levels of CCL2 which can stimulate prostate cancer cell NF-κB activity and invasion." (PMID 26317041, 2015). "Co-cultures with monocyte-lineage cell lines stimulated increased prostate cancer cell invasion through increased CCL2 expression and increased prostate cancer cell NF-κB activity." (PMID 26317041, 2015). "Prostate cancer cell invasion and CCL2 expression induced in the co-cultures was inhibited by Lactacystin and Bay11-7082 NF-κB inhibitors." (PMID 26317041, 2015). "The increased prostate cancer cell invasion depended on high CCL2 levels and was significantly inhibited by CCL2 neutralizing antibodies or treatment with a biochemical CCR2 inhibitor." (PMID 26317041, 2015). "These experiments taken together show that the co-cultures and recombinant CCL2 protein similarly stimulated prostate cancer cell invasion and NF-κB activity." (PMID 26317041, 2015). "Recombinant CCL2 protein stimulated prostate cancer cell invasion in a dose-dependent manner, similar to the co-cultures with monocyte-lineage cells." (PMID 26317041, 2015). "CCL2 is expressed in clinical prostate cancer tissues and its expression has been correlated with Gleason's score and pathological stage." (PMID 26317041, 2015). "Treatment of PC-3 High Invasive prostate cancer cells with recombinant human CCL2 protein induced dose-dependent nuclear NF-κB p65 DNA binding activity." (PMID 26317041, 2015). "The data in this study showed that increased prostate cancer cell invasion and NF-κB activation were induced by high CCL2 expression found in the co-cultures." (PMID 26317041, 2015). "In the present study, the prostate cancer cells and co-cultures also expressed high levels of IL-6, IL-8 and Gro-α; however, only CCL2 levels increased significantly in the co-cultures with monocytes." (PMID 26317041, 2015). "The highly invasive LM8 osteosarcoma cell line exhibit significant migratory ability, and CCL2 has been found to induce the migration of bladder and prostate cancer cells." (PMID 25695619, 2015). "Co-cultures with monocytes also showed that CCL2 expression and prostate cancer cell NF-κB activity were required for monocyte-induced prostate cancer cell invasion." (PMID 26317041, 2015). "Prostate cancer cell invasion was induced by recombinant CCL2 in a dose dependent manner, similar to co-cultures with monocytes." (PMID 26317041, 2015). "Combined inhibition of both CXCL8 and CXCL12 signaling was more effective in inhibiting fibroblast-promoted cell motility while repression of CXCL8 attenuated CCL2-promoted proliferation of prostate cancer cells." (PMID 24970800, 2014).
prostate carcinoma (continued). "Our functional experiments establish that CXCL12 and CCL2 act upon prostate cancer cells to induce very different responses." (PMID 24970800, 2014). "Further experiments focused on characterizing the regulation of CXCL12 and CCL2 across our panel of prostate cancer cells and representative stromal cell lines." (PMID 24970800, 2014). "Overexpression and increased activity of three specific chemokines termed CCL2, CXCL12 and CXCL8 have been strongly implicated in the progression of prostate cancer." (PMID 24970800, 2014). "CXCL12-induced migration of PC3 cells and CCL2-induced proliferation of prostate cancer cells were dependent upon intrinsic CXCL8 signaling within the prostate cancer cells." (PMID 24970800, 2014). "Accordingly, further experiments investigated the importance of stromal-derived CCL2 signaling on prostate cancer cell proliferation/viability." (PMID 24970800, 2014). "Increased CCL2 expression in prostate cancer (PCa) cells enhanced metastasis via macrophage recruitment." (PMID 23982944, 2013). "In prostate cancer, recruiting pro-angiogenic macrophages into primary and metastatic tumors is one of the mechanisms by which MCP-1/CCL2 promotes tumorigenesis and metastasis." (PMID 24314323, 2013). "The C-C chemokine ligand 2 (CCL2) stimulates migration, proliferation, and invasion of prostate cancer (PCa) cells, and its signaling also plays a role in the activation of osteoclasts." (PMID 23698775, 2013). "It has also been reported that CCL2 controls the extent of autophagy in human prostate cancer, and autophagy is pivotal for the survival and differentiation of monocytes." (PMID 24453432, 2013). "Recombinant human CCL2 induces dose-dependent prostate cancer cell proliferation in vitro and this pro-growth function is accomplished by the activation of the phosphatidylinositol 3-kinase (PI3K)/AKT pathway." (PMID 23946783, 2013). "Unexpectedly, the systemic administration of anti-CCL2 antibodies in prostate cancer mouse models only slightly attenuated the proliferation of tumor cells likely due to the "rescue" of the CCR2+ tumor cells by alternate chemokine ligands." (PMID 21943176, 2011). "Several other types of cancer cells, including prostate cancer, breast cancer, and myeloma cells, have also been demonstrated to express CCL2 and its receptor CCR2, both of which are correlated with prostate cancer development." (PMID 21826248, 2011). "Additionally, CCL2, secreted by AR-inhibited prostate cancer cells, induces FGF8b secretion from stromal cells within the tumor microenvironment, which in turn enhances KRAS activation." (PMID 42069672, 2026). "In prostate cancer, CCL2 has been shown to be involved in the formation of a metastatic niche." (PMID 39874810, 2025). "Previous studies indicated that GDF15 from prostate cancer cells (PCa) stimulates bone marrow mesenchymal stem cells to differentiate into osteoblasts and enhances CCL2 expression, which attracts the tumour to bone surfaces and contributes to PCa bone metastasis." (PMID 40292733, 2025). "Curcumin blocks CCL2-induced adhesion, invasion, and motility of prostate cancer cells." (PMID 40076892, 2025). "CCL2 serum concentration in prostate cancer patients was not statistically significantly associated with clinical progression or mortality outcomes." (PMID 39199567, 2024). "PA-activated GPRs/KLF7/CCL2 pathway in BMA facilitates prostate cancer growth and metastasis." (PMID 38221626, 2024). "Targeting CCL2 using its neutralizing antibody has been successful in mouse xenograft models in preventing prostate cancer metastasis; however, it was reported that accelerated relapse and metastasis may occur once the antibody administration is interrupted." (PMID 36672395, 2023). "Similarly, co-culture of prostate cancer cells with macrophages showed enhanced migratory abilities while cytokine analysis revealed CCL2 as the most abundant cytokine expressed by TAMs." (PMID 36836690, 2023).
prostate carcinoma (continued). "In prostate cancer, CCL2 has been reported to directly induce proliferation and migration of PC cell lines via activation of phosphoinostitide-3-kinase (PI3K)/serine-threonine kinase (Akt) signaling.This led us to consider CCL2 as a potentially useful PC biomarker." (PMID 36289628, 2022). "Similarly, during the development of bicalutamide resistance, CCL2 induces increased migration and invasion of prostate cancer cells by promoting AKT phosphorylation." (PMID 36077785, 2022). "Many studies on CCL2′s role in prostate cancer have described migration capacity and metastasis." (PMID 36289628, 2022). "The risk of developing visceral metastases may be very low in the group with low CCL2 levels at the time of prostate-cancer diagnosis." (PMID 36289628, 2022). "ASC-J9 could also inhibit the proliferation and metastasis of prostate cancer by regulating pSTAT3-C-C motif chemokine-2 (CCL2) signal transduction through an AR-dependent pathway via inhibiting the expression of the protein inhibitor of STAT3 (PIAS3)." (PMID 34295247, 2021). "Because the interaction between cancer cells and the host microenvironment is a vital component of tumorigenesis, the results of our microarray data analysis led us to focus on CCL2/CCR2 for examination of its relationship with HOXA11-AS in both prostate cancer cells and osteoblasts." (PMID 33514011, 2021). "Moreover, they showed that TNFα inhibition with etanercept in castration-resistant prostate cancer cells blocked enzalutamide-induced CCL2 protein secretion and mRNA expression." (PMID 33540543, 2021). "It was reported that CCL2 could protect prostate cancer PC‐3 cells from autophagic death and prolong the survival of tumour cells in serum‐free conditions via activating PI3K/AKT signalling." (PMID 34464477, 2021). "We hypothesized that HOXA11-AS may be transferred from prostate cancer cells to osteoblasts, possibly via EVs, to promote CCL2 expression in the recipient cells." (PMID 33514011, 2021). "HOXA11-AS-regulated CCL2/CCR2 may modulate the expression of HOXB13/HOXA11-AS-regulated integrins in prostate cancer; however, this interaction requires further investigation in future studies." (PMID 33514011, 2021). "Similarly, in a colon and prostate cancer model, CCL2 recruited cytotoxic T cells to the tumor microenvironment, which was prevented through natural nitration of intratumoral CCL2." (PMID 34503058, 2021). "Moreover, in prostate cancer, C-C motif chemokine ligand 2 (CCL2) is a main target of PRC1, and the H3K27me3 inhibitory marker that is bound with CBX7 is relatively low in the promoter region of the CCL2 gene, which leads to massive production of CCL2." (PMID 34659360, 2021). "During bone metastasis of prostate cancer, osteoblasts and BMECs stimulated by prostate-derived parathyroid hormone-related protein increase the secretion of CCL2 that could enhance osteoclastic activity and prostate cancer growth in bone." (PMID 33403387, 2021). "Furthermore, in-vitro osteoclast formation and in vivo tumor volume were diminished upon transfecting prostate cancer cells with shRNA against CCL2." (PMID 32585812, 2020). "Since two previously defined tumor-associated proinflammatory chemokines (CXCL1 and CCL2) were also detected in addition to the IL1RN, we asked whether there was a correlation in a human prostate cancer clinical dataset." (PMID 33322099, 2020). "CCL2 may be a starting point for subsequent chemokine cascades inducing prostate cancer cell activation." (PMID 33297571, 2020). "In addition, increased expression of CCL2 promotes prostate cancer growth and metastasis through TAM infiltration." (PMID 32971847, 2020). "The NR2C2 also increased prostate cancer invasion by altering TGFβR2/p-Smad3 signalling by decreasing miR-373-3p expression and further, promotes prostate cancer metastasis through upregulation of CCL2/CCR2 signalling." (PMID 33113804, 2020).
prostate carcinoma (continued). "Moreover, inhibition of CCL2 by carlumab combined with docetaxel significantly reduced tumor burden compared with docetaxel alone in prostate cancer xenograft model mice." (PMID 32824865, 2020). "CCL2 produced by adipocytes enhances the growth and invasion of prostate cancer cells." (PMID 32824865, 2020). "Prostate cancer and stromal cells secrete CCL2, which strongly recruits macrophages." (PMID 30736371, 2019). "Moreover, we also observed that PKCζ knockout remarkably impaired the secretion of CCL2 by prostate cancer cells and less infiltration of monocyte/macrophages into the tumors initiated from the 26A cell clone." (PMID 30705401, 2019). "Interestingly, we found that PKCζ regulates prostate cancer cell secretion of substantive amounts of CCL2 and promote TAM recruitment." (PMID 30705401, 2019). "Moreover, we found that PKCζ regulates the expression of lymphangiogenic factors and the secretion of CCL2 by prostate cancer cells, which is important for the recruitment of monocytes/macrophages and lymphangiogenesis." (PMID 30705401, 2019). "The destruction of bone by osteoclasts triggers the release of growth factors that support tumor growth, while the inhibition of these cells with neutralizing antibodies or shRNAs for CCL2 significantly impairs prostate cancer-induced formation of osteoclasts and bone resorption." (PMID 29594035, 2018). "The combination treatment reduced CCL2 in prostate cancer cells." (PMID 29386061, 2018). "On the other hand, an anti-metastatic activity of the axis CCL2-CCR2 has also been reported, as CCL2 expression levels in prostate cancer correlate with the degree of tumor aggressiveness, and absence of CCL2 in cervical cancer has been associated with relapse-free survival." (PMID 30591657, 2018). "Moreover, the combination treatment inhibited CCL2 secretion by prostate cancer cells more strongly than 5 μM DT did." (PMID 29386061, 2018). "Furthermore, the secretion of PTHrP from prostate cancer modulated osteoblasts, including CCL2 upregulation." (PMID 29642534, 2018). "Moreover, within a model of bone metastasis established by intratibia injection of prostate cancer cells, a paracrine interaction between the cancer cells and osteoblasts exists where prostate cancer-derived PTHrP induces CCL2 secretion in the osteoblasts." (PMID 29642534, 2018). "To validate the critical role of CCL2 in controlling the migration ability of DT-treated prostate cancer cells, we investigated the effects of DT or combined treatment with IR (5 μM DT plus 5 Gy IR) and with or without CCL2 on the migration ability of prostate cancer cells." (PMID 29386061, 2018). "Inhibition of CCL2 by I3C or DIM in the prostate cancer cells may indirectly minimize inflammation in tumor sites, influence tumor microenvironment and prevent prostate cancer development." (PMID 29364159, 2018). "However, DT and combined treatment with IR (5 μM DT plus 5 Gy IR) considerably inhibited the secretion of CCL2 by prostate cancer cells." (PMID 29386061, 2018). "Stimulation of prostate cancer cells with CCL2 was found to induce CCR2 production." (PMID 28039457, 2017). "Furthermore, DT can inhibit the migration of prostate cancer cells by interrupting the crosstalk between prostate cancer cells and macrophages via the inhibition of the CCL2/STAT3 axis." (PMID 28157698, 2017). "Interference with this pathway by administration of CCR2 antagonist, CCL2 neutralizing antibody, or PI3 kinase inhibitor or by knockdown of CCL2 in prostate cancer PC3 cells all resulted in decreased tumor formation, smaller tumor size, and less metastases in vivo." (PMID 29379802, 2017). "CCL2 is profoundly expressed in osteoporotic bone and prostate cancer-induced bone resorption." (PMID 28424660, 2017). "Additionally, increased CCL2 expression in prostate cancer cells has been demonstrated to encourage metastasis through macrophage recruitment." (PMID 28157698, 2017).
prostate carcinoma (continued). "Together, emerging evidence suggests that targeting the CCL2/STAT3–Skp2 pathway may offer therapeutic benefits to patients with prostate cancer." (PMID 28157698, 2017). "Moreover, tumor-derived IL-8 amplified stroma-derived CCL2-stimulated proliferation and promoted CXCL12-mediated invasion of PTEN-deficient prostate cancer cells." (PMID 28783760, 2017). "Additionally, increased CCL2 expression in prostate cancer cells encourages metastasis through macrophage recruitment." (PMID 28157698, 2017). "This suggests that DT may inhibit the migration of both macrophages and prostate cancer cells by blocking several cytokines, including CCL2, which is the principal cytokine during DT treatment." (PMID 28157698, 2017). "Double screening using serum PSA and CCL2 may reduce unnecessary biopsies and facilitate more accurate diagnosis of prostate cancer." (PMID 26701731, 2016). "The CCL2 ELISA data showed that autocrine CCL2 levels were significantly increased in the selected mig cells with increased in vitro migration ability, implicating increased autocrine production of CCL2 by prostate cancer cells as a key step in the promotion of prostate cancer cell migration." (PMID 26701731, 2016). "Given the extensive reports on CCL2 expression in prostate cancer, we chose to utilize CCR2." (PMID 27177227, 2016). "Importantly, ASC-J9® also functions through a AR-independent pathway to modulate CCL2 in prostate cancer." (PMID 27564257, 2016). "Indeed, CCL2 appears to be a promising biomarker as it was overexpressed in tissue and serum samples of prostate cancer patients, and its expression correlated with Gleason score and pathologic state, and a more aggressive phenotype." (PMID 26885690, 2016). "Therefore, we investigated the validity of CCL2 as a complementary biomarker to PSA for prostate cancer." (PMID 26701731, 2016). "Therefore, it is reasonable to combine PSA and CCL2 as biomarkers to improve the prediction of prognosis of patients with prostate cancer." (PMID 26701731, 2016). "However, to our knowledge, this report first demonstrates that CCL2 in monocyte co-cultures activated prostate cancer cell invasion through increased NF-κB activity." (PMID 26317041, 2015). "The prostate cancer epithelium contained CCL2 positive cells." (PMID 26317041, 2015). "CCL2 and NF-κB may be useful therapeutic targets to interfere with inflammation-induced prostate cancer invasion." (PMID 26317041, 2015). "In addition, studies of prostate cancer (PCa) patient serum and/or tumor tissue samples support a role for CCL2 in ADT-induced metastasis." (PMID 26327448, 2015). "Moreover, prostate cancer cell invasion stimulated by monocytes or recombinant CCL2 depended on prostate cancer cell NF-κB activity." (PMID 26317041, 2015). "Moreover, existing reports in the literature demonstrated that CCL2 had a significant role in promoting prostate cancer cell extravasation into the bone microenvironment and also contributing to breast tumor metastasis to brain." (PMID 25993304, 2015). "The increased prostate cancer cell nuclear c-Rel and NF-κB p65 expression in clinically advanced prostate cancer tissues where increased macrophage counts and CCL2 expression have been observed further supports the role of NF-κB activity in prostate cancer progression." (PMID 26317041, 2015). "Furthermore, CXCL8 signaling also increased the expression of CXCR4 and CXCR7 (the receptors mediating the biological activity of CXCL12) and CCR2 (a receptor activated by the ligand CCL2) in both PTEN-expressing and PTEN-deficient prostate cancer cells." (PMID 24970800, 2014). "Furthermore, repression of CXCL8 signaling reduced the sensitivity of prostate cancer cells to these effects of CCL2." (PMID 24970800, 2014). "In prostate cancer cells, the interaction of CCL2 and CCR2 induced STAT3 activation." (PMID 25405202, 2014).